SCD (stearoyl-CoA desaturase)
Diseases named in the same sentence as SCD in open-access papers (continued):
Sharing a sentence is not in itself a finding about the gene and the disease.
colorectal cancer (49 papers, 2016 to 2026). A primary or metastatic malignant neoplasm that affects the colon or rectum. "Other authors found that oleic acid promotes cancer stemness by the up-regulation of stearoyl-CoA-desaturase (SCD), which is associated with disease progression in colorectal cancer patients." (PMID 39859345, 2025). "CYP4F11, one of omega FA metabolizing enzymes, can metabolize the compounds into irreversible inhibitors of stearoyl CoA desaturase, and its expression level is predominantly and independently associated with the OS in colorectal cancer." (PMID 35432381, 2022). "One study revealed that upregulation of genes (ABCA1, ACSL1, AGPAT1, and SCD) related to lipogenesis and cholesterol synthesis pathways was associated with poor survival outcomes in colorectal cancer patients." (PMID 34557266, 2021). "These images showed that AQP8 and NR5A2 exhibited low staining intensity in colorectal cancer tissues, whereas SCD and TIMP1 showed high staining intensity." (PMID 41438584, 2026). "miR-215 interferes with cell migration and invasion by targeting stearoyl-CoA desaturase in colorectal cancer." (PMID 36467881, 2022). "In the years since those reviews were published, increased expression of SCD has been reported in an ever-growing list of cancer types including breast, colorectal, ovarian, endometrial, bladder, colorectal cancer, and clear-cell renal cell carcinoma." (PMID 33413672, 2021). "The acyl-CoA synthetase/stearoyl-CoA desaturase (ACSL/SCD) lipid network fuels migratory and invasive properties through EMT induction and is associated with an increased risk of relapse in colorectal cancer patients." (PMID 31744117, 2019). "The genomic coding sequence of ABCA1, ACSL1, AGPAT1 and SCD genes, as well as, their differential expression in a genome-wide expression meta-analysis in colorectal cancer patients were explored." (PMID 29464044, 2018). "Herein, by using a biologically annotated compound library, we performed a large-scale combination screening with Stearoyl-CoA desaturase-1 (SCD1) inhibitor, T-3764518, which partially inhibits colorectal cancer cell proliferation." (PMID 28704514, 2017). "Interestingly, the ACSL/SCD axis targeted by miR-19b-1 was later exploited by the same group in colorectal cancer as a promising therapeutic approach." (PMID 35054987, 2022). "Interestingly, the accumulation of palmitate during SCD inhibition stimulated de novo ceramide synthesis, which activates apoptosis in colorectal cancer cells." (PMID 33413672, 2021). "Subsequent studies have reported that aspirin effectively diminishes SCD-mediated MUFA production and induces ferroptosis in colorectal cancer cells." (PMID 40535804, 2025). "For example, T-3764518, a novel oral small molecule inhibitor of SCD, has demonstrated efficacy in inhibiting the growth of HCT-116 cell xenografts in mouse models of colorectal cancer." (PMID 39351232, 2024). "As expected, tumor-derived organoids highly expressed in vivo tumor-specific genes, many of which have been widely reported to be closely related to colorectal cancer progression and metastasis, such as PROCR, SCD, BMP4, CEACAM6, TESC, and TGFBI." (PMID 35484598, 2022). "A previous study showed that blocking stearoyl-CoA desaturase 1 (SCD1) expression or function inhibited the survival of CSCs, but not bulk colorectal cancer cells in vitro and in vivo." (PMID 36147494, 2022). "Finally, regarding lipid metabolism, overexpression of acetyl-CoA synthases (ACSL1 and ACSL4) as well as stearoyl-CoA desaturase (SCD), induce EMT and correlate with poor prognosis in colorectal cancer." (PMID 35054987, 2022). "Colorectal cancer (CRC) lipid signature, defined from a limited lipid-related genes expression profiling, reveals four genes (ABCA1, ACSL1, AGPAT1 and stearoyl-CoA desaturase (SCD)) overexpressed only in stage II CRC patients with a high risk of relapse." (PMID 26807644, 2016).
colon cancer (47 papers, 2012 to 2025). "For example, the lncRNA-UPAT together with the protein associated transcript UHRF1 up-regulate SCD-1 and Sprouty 4, a siRNA required for the survival of colon tumor cells." (PMID 33050166, 2020). "We reported a statistically significant 77% decrease in colon cancer risk with highest quartile of the oleic:stearic acid ratio, reflecting increased SCD-1 activity." (PMID 29872717, 2017). "The combined analysis of these 4 genes, ABCA1, ACSL1, AGPAT1 and SCD, constitutes a metabolic-signature (ColoLipidGene) able to accurately stratify stage II colon cancer patients with 5-fold higher risk of relapse with strong statistical power in the four independent groups of patients." (PMID 25749516, 2015). "For example, lower SCD expression has been observed in glioblastoma, and individual patients with liver cancer and colon cancer can exhibit variable levels of SCD expression." (PMID 41421797, 2025). "The study also showed that SULT2B1 facilitates lipid metabolism and promotes colon cancer cell metastasis by interacting directly with stearoyl-CoA desaturase (SCD1), which is involved in lipid metabolism." (PMID 39280099, 2024). "Colon cancer progression seems to be related with other oncometabolites that are part of the acyl-CoA synthetase/stearoyl-CoA desaturase (ACSL/SCD) lipid network." (PMID 37686573, 2023). "We also found reduced mRNA levels of key enzymes of the FA biosynthetic pathway in AhR KO colon cancer cells, in particular of stearoyl-CoA desaturase 1 (SCD1)." (PMID 36077780, 2022). "Despite this apparent difference in the role of SCD in tumorigenesis in colon cancer and disease progression in other cancer types, inhibition of SCD activity can be rescued by oleate supplementation, but not palmitate." (PMID 33413672, 2021). "The inhibition of SCD activity or SCD knockdown has been reported to limit proliferation of various types of cancer cells, including colon cancer cells." (PMID 34206240, 2021). "Immunohistochemistry (IHC) of tissue microarray (TMA) samples showed that SCD expression in individual patients within a cancer type such as liver and colon cancer was variable, but this variability was much greater in GBM." (PMID 33568479, 2021). "Our present results also confirmed an enhanced SCD expression in purified primary colon cancer cells, as well as an increased production of numerous MUFAs and PUFAs." (PMID 34206240, 2021). "We evaluated stearoyl-CoA desaturase 1 (SCD1) as a novel target for CSC-selective elimination in colon cancer." (PMID 33430034, 2021). "In fact, some studies have demonstrated that SCD-1 and MUFAs play critical roles in the maintenance of stemness in cancer stem cells, becoming potential therapeutic targets in ovarian or colon cancers." (PMID 34476741, 2021). "For example, the network miR-544a, miR-142, and miR-19b-1 were described as key controllers of the metabolic axis of activation and desaturation, ACSLs-1, -4 and SCD in colon cancer cells." (PMID 33050166, 2020). "Here we describe a metabolic acyl-CoA synthetase/stearoyl-CoA desaturase ACSL/SCD network causing an epithelial-mesenchymal transition (EMT) program that promotes migration and invasion of colon cancer cells." (PMID 26451612, 2015). "Increased levels of such PLs could be attributed to increased endogenous FA synthesis due to overexpression of key enzymes (FA synthase and stearoyl-CoA desaturase) in cancer tissue, including colon cancer microenvironment." (PMID 31999740, 2020). "The previously reported lipid metabolism-related axis, Acyl-CoA synthetases/ Stearoyl-CoA desaturase (ACSLs/SCD), stimulates colon cancer progression and metformin is able to rescue the invasive and migratory phenotype conferred to cancer cells upon this axis overexpression." (PMID 31339921, 2019).
colon cancer (continued). "Our main findings included statistically significant inverse associations with colon cancer risk for higher levels of the essential PUFAs α-linolenic and linoleic acids, the major contributing MUFA oleic acid, and SCD-1 index reflecting increased synthesis of oleic acid." (PMID 29872717, 2017). "Inhibition of SCD by expression of antisense RNA reduced tumour formation in human lung adenocarcinoma cancer cells while pharmacological inhibition of SCD was effective in blocking the growth of gastric and colon cancer cells." (PMID 27042297, 2016). "Collectively, these results imply that ACSL1, ACSL4 and SCD increased expression might act as a marker of poor prognosis which contributes to reduced disease free survival of colon cancer patients." (PMID 26451612, 2015). "Thus, ACSL/SCD network stimulates colon cancer progression through conferring increased energetic capacity and invasive and migratory properties to cancer cells, and might represent a new therapeutic opportunity for colon cancer treatment." (PMID 26451612, 2015). "In colon cancer cells, a cooperative metabolic network comprising overexpression of the Acyl-CoA synthetases ACSL1, ACSL4 and the related enzyme SCD induces EMT and increases cellular migration and invasion." (PMID 34073989, 2021). "Along with SCD, we also found FADS2 expression and activity to be significantly increased in colon tumor cells." (PMID 34206240, 2021). "For this reason, we evaluated the combined effect on colon cancer cell viability of Triacsin C, a specific inhibitor of ACSL, and the SCD inhibitor A939572, both previously reported to reduce tumor growth both in vitro and in vivo." (PMID 26451612, 2015). "uncovered that inhibiting SCD expression or function selectively excludes colon cancer stem cells through apoptosis, primarily by suppressing the Wnt and Notch signaling pathways." (PMID 40084144, 2025). "The model including the four LMGs (ABCA1, ACSL1, AGPAT1 and SCD) is proposed as a prognostic marker of colon cancer with stage II, but not effective in all stages of colon cancer." (PMID 37055842, 2023). "For example, stearoyl‐CoA desaturase (SCD) and long‐chain fatty acyl synthetase (ACSL) 1 and 4 cooperate to induce epithelial‐to‐mesenchymal transition resulting in an increased invasion potential of colon cancer cells." (PMID 33052601, 2021). "For this purpose we generated human colon cancer stable cell lines overexpressing either ACSL1, ACSL4 or SCD (ACSL1 cells, ACSL4 cells, and SCD cells, respectively) or the three genes simultaneously (x3 cells), transducing the DLD-1 CRC cell line with specific lentiviruses." (PMID 26451612, 2015).
gastric cancer (47 papers, 2020 to 2026). A primary or metastatic malignant neoplasm involving the stomach. "Akin to CDO1, stearoyl-CoA desaturase 1 (SCD1), an enzyme associated with the endoplasmic reticulum that is significantly upregulated in gastric cancer tissues, is implicated in the conversion of saturated fatty acids to monounsaturated fatty acids." (PMID 38370477, 2024). "SCD or stearoyl CoA desaturase-1 is implicated in fatty acid synthesis and has been associated with metabolic disorders and gastric cancer." (PMID 35132337, 2022). "For instance, DHPO, an allosteric covalent inhibitor of USP7, has been shown to inhibit gastric cancer proliferation and metastasis both in vitro and in vivo by downregulating stearoyl-CoA desaturase (SCD) and promoting ferroptosis." (PMID 41213937, 2025). "For instance, USP7 has been shown to suppress ferroptosis by activating stearoyl-CoA desaturase in gastric cancer, whereas USP8 knockdown enhanced ferroptosis through inhibiting GPX4 in CRC." (PMID 40962058, 2025). "A recent study demonstrated that ADAR1-mediated A-to-I editing on the 3ʹ-UTR of stearoyl-CoA desaturase (SCD1) augments SCD1 mRNA stability in gastric cancer cells." (PMID 39126156, 2025). "The inhibition of SCD by a small molecule inhibitor (A939572) can impair the proliferation of gastric cancer cells." (PMID 35785165, 2022). "In addition, DHPO has been identified as a potent USP7 inhibitor, which has been found to induce ferroptosis in gastric cancer cells by targeting the deubiquitination of Stearoyl-CoA Desaturase mediated by USP7." (PMID 40136417, 2025). "SCD inhibitors can selectively target underdeveloped cells of gastric organoids in vivo, which may inhibit the occurrence of gastric cancer." (PMID 41421797, 2025). "For example, Stearoyl-CoA desaturase (SCD1) accelerated lipid droplet formation to alleviate chemotherapy-induced ER stress and increase drug resistance in gastric cancer." (PMID 37858219, 2023). "In gastric cancer tissues and cells, SREBP-1c is activated and promotes the expressions of FASN and SCD-1 to mediate malignant phenotypes, which has been identified as a potential target for the treatment of gastric cancer." (PMID 35912181, 2022). "Consistent with our transcriptomic findings, LGALS9 treatment upregulated the expression of genes involved in cholesterol metabolism (NPC2, APOA) and PPAR signalling (SCD, PLIN2, FABP1), suggesting that LGALS9‐P4HB interaction modulates lipid metabolism in gastric cancer cells." (PMID 40534096, 2025). "Oleic acid (EA), produced via stearoyl-CoA desaturase (SCD)-dependent fatty acid desaturation, promotes the proliferation and survival of dysplastic gastric epithelial cells, thereby establishing an energy-supply chain through carcinogenic fatty acid metabolism during gastric cancer development." (PMID 40977700, 2025).
prostate carcinoma (41 papers, 2006 to 2025). A carcinoma that arises from epithelial cells of the prostate gland. "Palmitoleic acid (an MUFA produced by SCD) was identified as being positively associated with prostate cancer aggressiveness." (PMID 40430008, 2025). "SCD has been shown to promote proliferation and disease progression in prostate cancer by affecting cellular signaling cascades and modulating androgen receptor transactivation." (PMID 39335669, 2024). "High ALDH1A1 and SCD expression were significantly correlated with prostate cancer’s transition from the hormone-sensitive to castration-resistant state." (PMID 39335669, 2024). "In functional studies, SCD overexpression promoted the proliferation, metastasis and invasion of prostate cancer cells, whereas downregulation inhibits these processes." (PMID 39351232, 2024). "SCD can protect cancer cells from oxidative stress and ferroptosis through mediated lipogenesis in prostate cancer with over-activation of PI3K-AKT-mTOR signaling." (PMID 35265613, 2022). "Although our results regarding decreased SCD expression in GBM are not consistent with the results of most studies on other types of neoplasms, a reduction in SCD expression has also been observed in prostate cancer." (PMID 32392704, 2020). "Down-regulation of SCD is known to suppress cell proliferation through regulation of monounsaturated fatty acids in prostate cancer cells." (PMID 32343721, 2020). "Second, we correlated overexpression of Myc with high levels of SCD-1 in prostate cancer, highlighting a novel cooperation between Myc and the regulation of lipid metabolism to induce autophagy as a survival/growth mechanism." (PMID 28452935, 2017). "This study demonstrates that SCD is deregulated in human breast and prostate cancers and essential for cancer cell survival and tumour growth." (PMID 27042297, 2016). "SCD also promotes proliferation and disease progression in prostate cancer by affecting cellular signaling cascades and modulating androgen receptor transactivation." (PMID 27042297, 2016). "In this study, we analysed the response of breast and prostate cancer cell lines to the depletion of SCD, a rate-limiting enzyme for the production of mono-unsaturated fatty acids." (PMID 27042297, 2016). "Benign prostate hyperplasia, prostate carcinoma and prostate adenocarcinoma samples also showed increased SCD expression." (PMID 27042297, 2016). "Most importantly, we found that depletion of SCD efficiently blocked the ability of prostate cancer cells to grow as orthotopic tumour xenografts, resulting in reduced tumour volume and prolonged survival of the host." (PMID 27042297, 2016). "Using functional genomics, we identified stearoyl-CoA desaturase (SCD), an enzyme that controls synthesis of unsaturated fatty acids, as essential in breast and prostate cancer cells." (PMID 27042297, 2016). "Taken together, these results demonstrate that SCD is expressed in breast and prostate cancers and that high levels of SCD expression are indicative of advanced disease." (PMID 27042297, 2016). "Furthermore, SCD, an enzyme that controls synthesis of unsaturated fatty acids, as essential in breast and prostate cancer cells, was also observed to be elevated in obese CRC." (PMID 38311726, 2024). "In addition, the WGCNA method was used to identify core genes, and when combined with DNBs, four genes including SCD, NARS2, ALDH1A1, and NFXL1 were found to be associated with androgen-related signaling pathways in prostate cancer cells." (PMID 39335669, 2024). "Our study found that DNBs and four genes (SCD, NARS2, ALDH1A1, and NFXL1), as relevant factors associated with androgen-related signaling pathways in prostate cancer cells, can be further used as indicators of PCa progression after androgen deprivation therapy." (PMID 39335669, 2024). "We found that SCD is overexpressed in breast and prostate cancers compared to normal tissues." (PMID 27042297, 2016).
prostate carcinoma (continued). "SCD expression is elevated in the tumors of many cancers, including esophageal cancer, hepatocellular adenoma and carcinoma, colorectal cancer, breast cancer, gastric cancer, thyroid cancer, lung adenocarcinoma, prostate cancer, and clear-cell renal cell carcinoma." (PMID 32392704, 2020). "Here we report a novel relationship between Myc and the Desat1 involved in the control of autophagy and sustaining growth in epithelial cells that may be conserved in tumor cells, as we show a strong correlation between the expression of c-Myc and SCD-1 in prostate cancer." (PMID 28452935, 2017). "Stearoyl-CoA desaturase (SCD) is an enzyme that controls the synthesis of unsaturated fatty acids and is essential in breast and prostate cancer cells." (PMID 39335669, 2024). "The key enzyme, stearoyl CoA desaturase (SCD), facilitates proliferation of prostate cancer cells through an AR dependent pathway." (PMID 34822423, 2021). "Other authors have observed that SCD1 inhibition (through SCD siRNA) affects the cardiolipin levels, promoting cytochrome C release and apoptotic cell death in breast and prostate cancer cells." (PMID 31936134, 2020). "To establish the consequences of SCD inhibition on cellular lipid composition, we determined concentrations of saturated, mono-unsaturated and poly-unsaturated FFAs in DU145 prostate cancer cells following SCD inhibition in low serum conditions." (PMID 27042297, 2016). "A functional genomics analysis showed that SCD inhibition altered the cellular lipid composition and impeded cell viability in the absence of exogenous lipids in prostate cancer cells." (PMID 39335669, 2024).